GLI1 (GLI family zinc finger 1)
Diseases named in the same sentence as GLI1 in open-access papers (continued):
Sharing a sentence is not in itself a finding about the gene and the disease.
colon carcinoma (continued). "We have demonstrated in human colon carcinoma cells that inhibition of the RAS/RAF pathway by U0126 decreases p-ERK protein expression and also inhibits GLI-luciferase activity and GLI1 mRNA and protein levels." (PMID 21860067, 2011). "The requirement for both GLI1 and GLI2 for sustained proliferation and survival of human colon carcinoma cell lines in vitro, including HT29, was demonstrated using siRNA technology." (PMID 20957031, 2010). "For example, GLI-1 expression was enhanced in 5-FU resistant cancer cells derived from colon cancer cells (LoVo) when compared with non-resistant cells." (PMID 32503256, 2020). "LTC4-induced 15-PGDH downregulated Wnt target genes in a GLI1-dependent manner with concurrent activation of the intestinal tumour suppressor CDX2, which positively regulates the expression of SI in colon cancer cells and is a prominent intestinal differentiation marker." (PMID 32814764, 2020). "In addition, dual targeting of GLI1 by arsenic trioxide and PI3K inhibitor LY294002 synergistically downregulated both the GLI1 protein level and GLI1 target genes BCL2 and CCND1, which resulted in decreased proliferarion of colon cancer cells." (PMID 30423843, 2018). "Furthermore, protein expression of SMO, Gli1, CD44, and CD133 was decreased in colon cancer cells in response to treatment with the SMO inhibitor cyclopamine." (PMID 27894099, 2016). "In our study, Prdx2, SMO, Gli1, and CD133 expression was verified in the colon cancer cell lines." (PMID 27894099, 2016). "Other studies reported that GANT-61 inhibits GLI1/GLI2 in colon cancer cells that are resistant to the SMO inhibitors cyclopamine and GDC-0449; this observation suggests SMO-independent Hh signaling pathway activation in colon cancer." (PMID 26843616, 2016). "Of interest, the predicted binding constants (KD) for GANT61-diamine-GLI1 (7.5 μM) or GANT61 inhibition of GLI-DNA binding (3.2 μM) are consistent with GANT61 concentrations of 10 μM-20 μM for 48 hr-72 hr exposures, required to induce cell death in human colon carcinoma cell lines." (PMID 24962990, 2014). "Hedgehog/Gli1 signaling related components, PTCH1 and Gli1, are over-expressed in colon tumor." (PMID 25386960, 2014). "Human colon cancer cells HT29 and SW480, exposed to GANT61 (20 μM), a small molecule inhibitor of GLI1 and GLI2, for 72 hr demonstrated reduced steady state levels of GLI1, GLI2 and hTERT proteins." (PMID 24086482, 2013). "Using a genetic approach to suppress GLI1 and GLI2 using GLI3R, hTERT expression could also be inhibited in colon cancer cells." (PMID 24086482, 2013). "Thus, canonical activation of GLI1 and GLI2 via SMO is important for the survival and proliferation of human colon carcinoma cells in vivo." (PMID 20957031, 2010). "Thus, using qRT-PCR, the expression of GLI1, PTCH1, GLI2 and SHH was determined in all human colon carcinomas examined." (PMID 20957031, 2010). "In cancer cell lines HT29 (colon cancer origin) and Panc1 (pancreatic origin), X-ray irradiation not only increased the expression of Shh and Gli1 at protein level, also induced the transcriptional activity of Gli1." (PMID 30235830, 2018). "We have previously demonstrated rapid inhibition of binding of the GLI1 and GLI2 transcription factors to target gene promoters (1 hr), reduced reporter activity specific to GLI-luciferase, and rapid inhibition of gene transcription in human colon carcinoma cell lines in response to GANT61." (PMID 27863397, 2016). "The results presented in this study indicated that the anticancer effect of celecoxib is selective in colon cancer cells; celecoxib may target cancer cells via the SMO-independent modulation of GLI1 activity, and Hh signaling may be significant in maintaining the malignant state of LoVo cells." (PMID 25295109, 2014). "Similar data were obtained using the colon cancer cell line HT29, demonstrating that the Ser408-dependent proliferation effect is not cell-type specific, but rather Gli1-specific." (PMID 26843621, 2016).
colon carcinoma (continued). "Similarly, the RAS-RAF pathway induces GLI1 and GLI2 transcriptional activity and increases mRNA and protein levels in a non-canonical manner in colon cancer cells." (PMID 31244888, 2019).
colorectal cancer (56 papers, 2013 to 2025). A primary or metastatic malignant neoplasm that affects the colon or rectum. "The glioma-associated oncogene-1 (Gli1) is a tumor-promoting factor that its upregulation enhances growth and invasion of colorectal cancer cells." (PMID 34769099, 2021). "A recent study reported that GLI1 expression is closely associated with FoxM1 expression and that GLI1 expression elevation promotes colorectal cancer metastasis via FoxM1 overexpression." (PMID 33214609, 2020). "The relevance of our data to colorectal cancer patients is reflected by the increasing risk of cancer relapse and poor treatment outcomes in patients with high GLI1 expression in the primary tumor." (PMID 28413604, 2017). "Furthermore, when GLI1 blockers were tested in laboratory models of BRAF-mutated colorectal cancer, they yielded promising results in reducing tumor growth by suppressing the NBS1 levels in BRAF-mutated cancers." (PMID 39851545, 2025). "Gli1 protein expression in colorectal cancer tissue correlates with several leading-edge cancer clusters, infiltration depth, lymph node metastasis, and the TNM stage of colorectal cancer." (PMID 40224487, 2025). "In colorectal cancer tissues, Gli1 is coexpressed with cancer stem cell (CSC) markers, including SOX9 and CD133." (PMID 40224487, 2025). "GLI1-positive mesenchymal cells in colorectal cancer tissues secrete Wnt, aiding in the maintenance and promotion of stem cell self-renewal." (PMID 38625488, 2024). "Downregulation of GLI1 in colorectal cancer inhibits cancer cell proliferation while involving activation of Wnt signaling." (PMID 38498906, 2024). "The presence of a primary cilium in colorectal cancer cells was correlated with the increased expression of the HH effector GLI1 and the recruitment of the SMO receptor, suggesting the potential for an autocrine pathway." (PMID 37048132, 2023). "RUNX3 was earlier shown to promote ubiquitination of MYCN in neuroblastoma and the Hedgehog pathway oncogenic transcription factor GLI1 in colorectal cancer cells." (PMID 37400551, 2023). "CCT2 was essential for antagonizing Gli-1 ubiquitination in colorectal cancer, especially under the hypoxic condition." (PMID 37500615, 2023). "It’s reported that circZNF609 sequestering microRNA-150 plays a role in promoting colorectal cancer progression by upregulating Gli1 expression." (PMID 35581586, 2022). "Overexpression of GLI1 in colorectal cancer cells induces more invasive growth in organoid 3D cultures as well as in soft agar colony formation." (PMID 34113570, 2021). "PGE2 treatment of colorectal cancer cells increased the abundance of Gli1 and Gli2 proteins, reaching maximum at approximately 1 h, with no appreciable effect on the expression of Gli3 protein." (PMID 34267186, 2021). "C-MYC, which is frequently over-amplified in colorectal cancer, has been confirmed to be another oncogene that activates GLI1 independently from Hh ligand-mediated signaling." (PMID 34113570, 2021). "We found that the majority of colorectal cancer patients had high-GLI1 expression, which was negatively correlated with CysLT2R, 15-PGDH, and Mucin-2 and overall survival compared with the low-GLI1 group." (PMID 32814764, 2020). "A previous study shows that aberrant overexpression of GLI1 promotes colorectal cancer metastasis via FoxM1 overexpression." (PMID 33214609, 2020). "Here, we investigated the involvement of Hedgehog (Hh)–GLI1 signalling, which is often hyperactivated in colorectal cancer." (PMID 32814764, 2020). "GLI1 inhibition was shown to revert chemo-resistance in organoids from colorectal cancer patients, and concurrently down-regulated cancer stem cells markers, such as c-Myc, CD44 and Nanog9." (PMID 32814794, 2020). "In the present study, we for the first time demonstrated that Hedgehog signal inhibitor decreased the resistance to 5-FU, Irinotecan and Oxaliplatin likely through the inhibition of GLI-1 expression using colorectal cancer patient-derived ALI organoids." (PMID 29642386, 2018).
colorectal cancer (continued). "Taken together, our data demonstrate the critical role of the GLI1 signaling axis for 5-FU resistance in colorectal cancer." (PMID 28413604, 2017). "The odd ratio for cancer relapse in high GLI1/GLI3 expression is 1.69, indicating that high expression of GLI1/GLI3 signaling molecules increases the risk of cancer relapse by 69% in colorectal cancer patients after chemotherapy." (PMID 28413604, 2017). "Our results indicate that elevated expression of GLI1 and the signaling molecules are an important mechanism for 5-FU resistance in colorectal cancer cells." (PMID 28413604, 2017). "In colorectal cancer, GLI1 overexpression inhibits Wnt signaling and colorectal cancer cell proliferation, even in cells that harbor a stabilizing mutation in β-catenin." (PMID 29088246, 2017). "So, we concluded that Gli1 also promoted colorectal cancer cells migration and invasion in a Foxm1-dependent manner in vivo." (PMID 27863385, 2016). "For example, in colorectal cancer, overexpression of Gli1 (a downstream component of the SHH signaling pathway) inhibits Wnt signaling and colorectal cancer cell proliferation, even in cells possessing the stabilizing mutation of β-catenin." (PMID 25713298, 2015). "Here, we report a loss-of-function mutation of PTCH1, a tumor suppressor in the Hh pathway, in a colorectal cancer that exhibits transcriptional upregulation of the downstream Hh gene GLI1." (PMID 24368541, 2013). "Based on this information, we can speculate that GRK2 affects GLI1 protein expression in the HH signaling pathway, participating in the regulation of colorectal cancer." (PMID 40224487, 2025). "Further investigation reveals that LINC01106 located in the nuclear could recruit FUS protein to Gli1 and Gli2 promoters, hence activating Gli1 and Gli2 transcription and promoting colorectal cancer formation." (PMID 35581586, 2022). "CCT2 was a vital determinant of survival in CRC (colorectal cancer) patients and could regulate the folding of Gli-1, a Hedgehog signaling factor in relation to hypoxia." (PMID 33815471, 2021). "The activation of the HH signal promoted EMT-related pathways, and GLI1 could bind to the promoter region of six ABC transporters in colorectal cancers." (PMID 34440799, 2021). "GLI-1 is known to be vital in cancer biology and overexpressed in colorectal cancer cells." (PMID 29642386, 2018). "It is thus predicted that agents inhibiting GLI1 activity may be effective in sensitizing colorectal cancer cells to 5-FU-based chemotherapy." (PMID 28413604, 2017). "Similarly, CRD-BP has been shown to bind to and stabilize GLI1 mRNA leading to elevated GLI1 protein and proliferation of colorectal cancer cells." (PMID 28182633, 2017). "GLI1 is known to be significantly overexpressed in colorectal cancer cells." (PMID 28413604, 2017). "As a major focus for our laboratory on Hh signaling, we proposed that GLI1 might be a vital factor of 5-Fu resistance in patients with colorectal cancer." (PMID 28413604, 2017). "Furthermore, we found that Gli1 promotes colorectal cancer cells metastasis in a Foxm1-dependent manner by activating EMT and PI3K-AKT signaling." (PMID 27863385, 2016). "For instance, in a study comprising 25 clinical samples of colorectal carcinoma, Shh expression was found upregulated and, interestingly, when GLI1 expression was analyzed by in situ hybridization, it was mainly found in the malignant crypts of adenocarcinomas." (PMID 26258070, 2015). "Both Wnt/β-catenin and Hedgehog/Gli1 signalings are abnormal activated in colorectal cancer." (PMID 25386960, 2014). "Similarly, CRD-BP binds to and stabilizes GLI1 mRNA leading to elevated GLI1 protein, transcriptional activation, and proliferation of colorectal cancer cells." (PMID 24622399, 2014).
colorectal cancer (continued). "Sonic hedgehog (Shh) and Indian hedgehog (Ihh) ligands are widely overexpressed in colorectal cancer-derived cell lines and in colorectal cancers, but the level of Hh pathway activity, as measured by the expression of the downstream effector GLI1, is highly variable." (PMID 24368541, 2013). "In addition, GLI binding sites in the promoter region of six ABC transporters, namely ABCA2, ABCB1, ABCB4, ABCB7, ABCC2 and ABCG1, were confirmed in a recent study, and the inhibition of GLI1 reduced the expression of these ABC transporters in colorectal cancer cells." (PMID 33440657, 2021). "Notably, a PCR analysis of primary human colorectal tumor samples that were previously shown to activate β-catenin and express high levels of CRD-BP was characterized by high levels of GLI1, which was consistent with those in a panel of established colorectal cancer cell lines." (PMID 34572373, 2021). "Furthermore, GLI1 contributed to Wnt/βcatenin–dependent proliferation of human colorectal cancer cells, and GLI1 transfection into cancer cells could rescue colony formation when Wnt/β–catenin signaling was inhibited." (PMID 34572373, 2021). "Variations in the GLI1 and PTCH1 levels were consistent with those observed between the various colorectal cancer cell lines." (PMID 37048132, 2023). "The clear correlation between GLI and ABC transporter proteins such as ABCA2, ABCB1, ABCB4, ABCB7, ABCC2, and ABCG1 was revealed by the use of GLI1 inhibitors, which led to reduced expression of ABC transporters in colorectal cancer cells." (PMID 37626893, 2023). "In human colorectal cancer (CRC), Gli1 regulates FOXM1 by directly binding to its promoter at BS4 (GCCCACCCA), which contributes to the proliferation of CRC cells." (PMID 30208972, 2018). "Small molecule inhibition of GLI1 and GLI2 has been shown to induce cell death in colorectal carcinoma cell lines." (PMID 26393651, 2015). "The aim of the present study is to investigate the effects of low concentrations of p,p′-DDE on colorectal cancer and the involved mechanism concerning oxidative stress and two critical CRC–related pathways, Wnt/β-catenin and Hedgehog/Gli1 signalings." (PMID 25386960, 2014). "A colorectal cancer study demonstrated that SHH, Gli1, and FOXM1 mRNA expression levels were higher in colorectal adenocarcinomas than in adjacent normal colon tissue." (PMID 24325450, 2013). "The current study indicates a beneficial survival impact of GLI1, contradicting many previous studies, reporting GLI1 as a potent manipulator in carcinogenesis and as a negative prognostic indicator in breast, gastric, and colorectal cancers." (PMID 40565349, 2025). "Recent studies have also confirmed that PARK7 promotes the proliferation and metastasis of colorectal cancer by activating the Hh and Wnt signaling pathways, and that PARK7 increases proteins involved in the Hh signaling pathway, including GLI1, GLI2, and PTCH1." (PMID 39276379, 2024). "A study in colorectal cancer demonstrated that increased RUNX3 protein expression resulted in both increased ubiquitination and proteasomal degradation of the oncogene GLI1, which is enhanced in the presence of suppressor of fused (SUFU), a negative regulator of GLI1." (PMID 36899853, 2023). "It has been shown that, during hypoxia in colorectal cancer, hypoxia activates the hedgehog pathway, CCT2 helps protein folding by binding to the oncogenic protein gli1, and a high expression of CCT2 and glii-1 enhances tumor invasion and migration in vivo and in vitro." (PMID 36119498, 2022). "Similarly, aberrant expression of oncogenic EGFR, which is responsible for the over-activation of GLI1 through RAS-RAF-MEK pathway, promotes colorectal cancer metastasis and chemotherapeutic resistance." (PMID 34113570, 2021). "Specific inhibition of GLI1 induces extensive cell death while the inhibition of Hh signaling at the level of SMO did not in colorectal cancers." (PMID 34113570, 2021).
colorectal cancer (continued). "Recent study showed that GLI-1 expression was elevated in 5-FU resistant colorectal cancer cell line LoVo-R compared with non-resistant one." (PMID 29642386, 2018). "In human basal cell carcinomas and colorectal cancer cells, FOXM1 is also a direct target of Gli1." (PMID 30208972, 2018). "Although the detailed mechanisms by which GLI-1 regulates the resistance remain unclear, further studies by using the ALI organoid system might contribute to overcoming chemoresistance in colorectal cancer patients." (PMID 29642386, 2018). "In this study, we addressed whether integration of the Gli1-Foxm1 axis and EGFR-PI3K-AKT pathway is a critical step in colorectal cancer metastasis." (PMID 27863385, 2016).